CASP1 (caspase 1)
Diseases named in the same sentence as CASP1 in open-access papers (continued):
Sharing a sentence is not in itself a finding about the gene and the disease.
Cerebral ischemia (continued). "This treatment reduced the expression of NLRP3, caspase-1, and IL-1β, and the occurrence of cell pyroptosis and inflammatory response, suggesting that the protective effect of EA on cerebral ischemia/reperfusion injury may be played by inhibiting the pyroptosis pathway dependent on caspase-1." (PMID 35600074, 2022). "To further investigate whether MFSCE attenuates neuroinflammation after cerebral ischemia, we determined the expression of NLRP inflammasome-associated proteins, including NLRP1, NLRP3, ASC, CL-caspase-1, CL-caspase-11, IL-1β, and IL-18 in the ischemic cortex using Western blotting." (PMID 35454994, 2022). "Therefore, it's essential to screen and design potential Caspase-1 inhibitors to reduce cerebral ischemia-reperfusion injury and protect brain function by reducing inflammation and pyroptosis, which provides a new idea for clinical treatment of the cerebral ischemia-reperfusion injury." (PMID 35193116, 2022). "Electroacupuncture (EA) can reduce neuronal injury caused by cerebral ischemia–reperfusion, and we speculated that EA can prevent neuronal pyroptosis after cerebral ischemia–reperfusion by regulating the nucleotide-binding oligomerization domain-like receptor protein 3 (NLRP3)/caspase-1 pathway." (PMID 35600074, 2022). "Furthermore, we found that the mRNA transcription levels of NLRP3, IL-1β, and caspase-1 in the core ischemic area were remarkably amplified in diabetic mice with cerebral ischemia-reperfusion injury, whereas this phenomenon was obviously attenuated by MCC950 pretreatment." (PMID 29853850, 2018). "Finally, caspase-1 knockout mice, as well as caspase-1 inhibitor- or dominant negative-treated mice, have been all reported to have significantly decreased neuronal cell death and brain deficits following cerebral ischemia." (PMID 27843532, 2016). "However, direct molecular evidence is lacking regarding how quercetin precisely regulates the NLRP3/Caspase-1/GSDMD core pyroptosis axis in microglia in cerebral ischemia models and whether it can directly target NLRP3 to inhibit this axis, thereby alleviating cerebral ischemic injury." (PMID 41892344, 2026). "Cerebral ischemia-reperfusion damage was alleviated to different degrees, suggesting that the NF-κB/NLRP3/Caspase-1/GSDMD signaling pathway is involved in the pathogenesis and healing of ischemic stroke." (PMID 39199474, 2024). "In summary, our results revealed that cerebral ischemia induced the upregulation of ROS and NLRP3, Caspase-1, and IL-1β expression, whereas HS reduced the levels of all these factors." (PMID 37371417, 2023). "Many endogenous danger signals produced by cerebral ischemia/reperfusion (I/R) injury activate NLRP3 inflammasome and convert pro-caspase 1 into cleaved caspase-1 (Cl-Caspase-1)." (PMID 35136042, 2022). "Cerebral ischemia also resulted in a significant increase of protein levels of the adaptor protein ASC, activated Caspase-1, and the cleavage product of inflammasomes, IL-1β (p < 0.05)." (PMID 34628598, 2022). "In cerebral ischemia, NLRP3 inflammasome activation evoked the cleavage of caspase-1, thereby cleaving GSDMD, pro-IL-1β, and pro-IL-18 to GSDMD-N, mature IL-1β, and IL-18, respectively." (PMID 34630845, 2021). "In this study, we used rat models to explore the effect of vx-765, a caspase-1 inhibitor, on BBB dysfunction after MCAO-induced cerebral ischemia." (PMID 33584203, 2020). "In cerebral ischemia, the NLR inflammasome assembles through the recognition of PAMPs and recruitment of pro-caspase-1 with the adapter protein ASC." (PMID 33013286, 2020). "To provide evidence of MCC950 to the protective effect of cerebral ischemia reperfusion in diabetic mice, we measured the mRNA levels of NLRP3, IL-1β, and caspase-1 in the boundary zone adjacent to the ischemic core." (PMID 29853850, 2018). "In models of brain ischemia, evidence for inflammasome activation has been reported with elevations in inflammatory proteins such as ASC, and caspase-1." (PMID 30217051, 2018).
Cerebral ischemia (continued). "Previous studies have also demonstrated that caspase-1 activation and subsequent GSDMD cleavage play key roles in pyroptosis and neuroinflammation in CNS diseases, such as cerebral ischemia and AD, and that the inhibition of caspase-1 activation can attenuate brain injury." (PMID 37921870, 2023).
glioma (41 papers, 2017 to 2025). A benign or malignant brain and spinal cord tumor that arises from glial cells (astrocytes, oligodendrocytes, ependymal cells). "miRNA-214 reduces cellular proliferation and migration in glioma cells by inhibiting the expression of caspase 1, a protein that is implicated in pyroptosis." (PMID 34764994, 2021). "However, in U87 and U251 glioma cells, simvastatin inhibited pyroptosis and caused cell death by inhibiting caspase-1, NLRP3, and IL-1β production." (PMID 36867378, 2023). "Although NLRP6 was reported to serve as a tumor suppressor in colorectal cancer, hepatocellular carcinoma, and gastric cancer, it was reported to restore immune evasion and radio-resistance in glioma through ASC/caspase-1/IL-1β axis." (PMID 38678251, 2024). "Berberine directly inhibits caspase-1 activation via the ERK1/2 signaling pathway in glioma cells, leading to inhibition of the expression of pro-inflammatory cytokines such as IL-1β and IL-18." (PMID 37723542, 2023). "The role of berberine, a potential therapeutic agent targeting caspase-1, an important hall marker of inflammasome activity, was investigated in a glioma cell line." (PMID 37723542, 2023). "MiR-214 suppresses proliferation and migration through inhibiting caspase 1-mediated pyroptosis in glioma U87 and T98G cells, which opens the avenue for a novel therapy to treat gliomas." (PMID 37142295, 2023). "Recent developments toward our understanding of the canonical pathway (the inflammasome-caspase-1-proinflammatory cytokine axis) of inflammasome activation in glioma have been expertly reviewed in depth." (PMID 37723542, 2023). "For example, berberine treatment inhibits glioma growth by inactivating caspase-1-mediated inflammatory cytokines via ERK1/2 regulation." (PMID 37723542, 2023). "Caspase-1 had an essential position in glioma growth, mobility, aggression, epithelial-mesenchymal transition, and anti-apoptosis." (PMID 37153540, 2023). "MiR-214–3p partially inhibited glioma cell growth and invasion by regulating caspase-1-mediated pyroptosis." (PMID 36867378, 2023). "The current research found a significant increase in Caspase-1 expression in glioma tissue and cell lines, mediating pyroptosis (an inflammatory form of cell death)." (PMID 37153540, 2023). "We found higher expression levels for CASP1 and CASP3 in glioma cell lines than in HEB cells; two risk factors thought to play an important role in glioma." (PMID 35964070, 2022). "As the correlations among Tim-3, Gal-9, NLRC4, and CASP1 were highly positive, we compared the expression levels of each gene in glioma and healthy tissue." (PMID 35216164, 2022). "In glioma, an inverse relationship between abundant caspase-1 expression and low expression of miRNA-214 was observed." (PMID 36209102, 2022). "Tim-3 or Gal-9 downregulation significantly decreased NLRC4 and caspase-1 expression in glioma cells." (PMID 35216164, 2022). "Tim-3/Gal-9 did not trigger IL-1β secretion but were strongly positively correlated with caspase-1 activity as they induced programmed cell death in glioma cells." (PMID 35216164, 2022). "We employed IHC to validate the protein expression of EZH2, LEF1, and CASP1 in 43 glioma tissues and matched paracancerous tissues." (PMID 36389690, 2022). "A fluorescent-labeled inhibitor of caspase (FLICA) analysis of caspase-1 was performed on the primary cells of each glioma grade." (PMID 35216164, 2022). "miR-214 inhibited the proliferation and migration of glioma cells through suppressing pyroptosis intermediated by caspase-1." (PMID 35445025, 2022). "Subsequent multivariate Cox regression analysis indicated that three genes, EZH2, LEF1, and CASP1, exhibited significant prognostic value for glioma." (PMID 36389690, 2022). "The NLRC4 inflammasome and caspase-1 expression levels were dramatically increased in glioma cells transfected with pcDNA harboring Tim-3 or Gal-9." (PMID 35216164, 2022).
glioma (continued). "The dysregulation of three necroptosis-related genes (EZH2, LEF1, and CASP1) was significantly related to the OS of glioma patients, especially those with older age, higher WHO grade, wildtype IDH status, and 1p19q codeletion status." (PMID 36389690, 2022). "BBR inhibits the inflammatory cytokine caspase-1 activation through ERK1/2 signaling as well as glioma cells’ subsequent development of IL-1 and IL-18." (PMID 34885950, 2021). "Nod-like receptor signaling molecules promote glioma angiogenesis by acting on downstream targets such as IL-1 and caspase-1." (PMID 34384424, 2021). "On the other hand, the increase of NLRP3, ASC, caspase-1, and IL-1β proteins in human glioma tissues is significantly correlated with higher World Health Organization grades." (PMID 33613533, 2020). "The protein expression of cleaved caspase-1 (activated form) was significantly increased in glioma tissues as compared to normal brain tissues." (PMID 31139563, 2019). "miR-214 suppresses cell growth and metastasis by modulating caspase-1-mediated cell pyroptosis in glioma cells." (PMID 31501419, 2019). "In addition, caspase-1 was previously shown to be involved in the induction of TRAIL-R2-mediated cell death in glioma cells." (PMID 38835345, 2024). "In this regard, the pharmacological inhibition of the inflammasome receptor protein, adaptor protein, caspase-1, and pro-inflammatory cytokines may facilitate glioma management." (PMID 37723542, 2023). "Furthermore, miR-214 plays an important role in restraining the proliferation and migration of glioma cells through targeting caspase-1-involved pyroptosis." (PMID 38016064, 2023). "In addition, several studies have demonstrated the inhibitory effect of miR-214 on the proliferation and migration of GBM cell lines through caspase-1-induced pyroptosis in gliomas." (PMID 38016064, 2023). "Besides, miRNA-214 can inhibit the proliferation and migration of glioma cells by targeting caspase-1, which is involved in pyroptosis." (PMID 36861130, 2023). "CASP1 plays an important role in upregulating the development of glioma." (PMID 36015199, 2022). "Next, we sought to identify drugs that can pharmacologically target this core gene and explored whether CASP1 can serve as a therapeutic target of glioma using specific drugs." (PMID 35433410, 2022). "Moreover, miRNA-214 was found to inhibit cellular proliferation and migration via caspase-1 dependent pyroptosis in glioma." (PMID 36209102, 2022). "In glioma, miR-214 suppresses cell proliferation and migration via caspase-1-mediated pyroptosis." (PMID 36059539, 2022). "Glioma malignancy and caspase-1 activity were positively correlated." (PMID 35216164, 2022). "In general, our results revealed that the CASP1 gene may represent a potential therapeutic target and that belnacasan might be a potential therapeutic drug for glioma." (PMID 35433410, 2022). "The modulation of pyroptosis intermediated by caspase 1 in glioma cells might inhibit cell proliferation and migration, suggesting a potential new therapy for glioma interventions." (PMID 35276059, 2022). "Furthermore, we demonstrated that mRNA expression of caspase-1 was also significantly upregulated in glioma tissues compared to normal brain tissues, suggesting that transcriptional upregulation contributes to increased protein expression of cleaved caspase-1." (PMID 31139563, 2019). "Therefore, we looked at the expression of differentially expressed genes, ASC/PYCARD, AIM2, and CASP1 under normal and inflammatory conditions in microglia and glioma cells." (PMID 31186453, 2019). "Thus, Tim-3 and Gal-9 may be significantly correlated with caspase-1 activation and, by extension, programmed cell death in glioma." (PMID 35216164, 2022). "We further questioned whether this caspase-1 is expressed in which cells in glioma." (PMID 35216164, 2022).
glioma (continued). "In C6 glioma cells, inhibition of NLRP3 through beta-hydroxybutyrate (BHB) reduces caspase-1 and suppresses cell migration, likely by reducing ACS oligomerization or preventing K+ efflux." (PMID 41291696, 2025). "In gliomas, knockdown of hsa_circ_0001836 significantly increased the expression of NLRP1, cleaved caspase-1 and GSDMD-N, and induced the pyroptosis of glioma cells." (PMID 36861130, 2023). "The differential gene analysis in the current study showed that CASP4 expression is associated with several other important molecules of pyroptosis, including GSDMD, CASP1, IL-18, and TLR2, in gliomas." (PMID 36713560, 2022). "We combined all tumor expression data from TCGA with GEPIA2 data and obtained differentially expressed genes that were correlated with CASP4 expression in gliomas, including GSDMD, CASP1, IL-18, and TLR2." (PMID 36713560, 2022). "We performed co-staining of the caspase-1 with microglia (Iba1+) and astrocyte (GFAP+), which play important roles in the pathology of gliomas." (PMID 35216164, 2022). "Next, its mRNA expression level in glioma cell lines (SW1783, SW1088, T98G, LN18, and A172) and HEB cell by qRT-PCR indicated that CASP1 and CASP3 expression overall showed overall an upward trend in glioma cell lines." (PMID 35964070, 2022). "U87MG and J3TBG Glioma cells were treated with CBD and VX-765 (Belnacasan, 50 μM), a caspase-1 inhibitor." (PMID 34456736, 2021). "In this study, we demonstrate that berberine significantly inhibits inflammatory cytokine Caspase-1 activation via ERK1/2 signaling and subsequent production of IL-1β and IL-18 by glioma cells." (PMID 31139563, 2019). "We have observed high HR (greater or equal to 0.5) for NLRC4, CASP1, NLRP12 and MSR1 genes in grade 3 & grade 4 glioma." (PMID 31186453, 2019). "A higher degree of CASP1 represented the core gene in the PPI network and might be more closely related to glioma prognosis." (PMID 35433410, 2022). "Notably, TIM-3/Gal-9 upregulates the expression of NLRC4 and caspase-1 but does not trigger IL-1β secretion in glioma." (PMID 41291696, 2025). "CASP1 displayed the highest mutation frequency, followed by Gasdermin C (GSDMC), while CASP3, Gasdermin B (GSDMB), Gasdermin E (GSDME), and GZAMB did not display any mutations in glioma samples." (PMID 35620284, 2022). "Furthermore, the expression levels of genes encoding NLR proteins (NLRP12, NOD2, NOD1, NLRC4, and NAIP), inflammasome adaptor molecules (PYCARD), and proinflammatory caspases (CASP1, CASP4, and CASP5) were significantly higher in glioma patients than in normal controls." (PMID 31133717, 2019). "Additionally, DNA methylation analysis demonstrated that the promoter methylation levels of AIM2, CASP1, CASP8, NLRP3, and ZBP1 are significantly lower in gliomas than in non-tumor brain tissues." (PMID 39901195, 2025). "However, the roles of CASP1, NOD1, NLRC4 and NLRP12 are not reported in relation to glioma." (PMID 31186453, 2019).
Hyperglycemia (41 papers, 2012 to 2025). An increased concentration of glucose in the blood. "Using Müller cells known to produce active caspase-1 and IL-1β under hyperglycemic conditions we confirmed that prolonged exposure to hyperglycemia leads to caspase-1/IL-1β/IL-1R1 feedback signaling causing sustained caspase-1 activity." (PMID 39483336, 2024). "Hyperglycemia causes oxidative stress in these cells, which in turn promotes inflammasome scaffolding, caspase-1 activation, and production of IL-1β." (PMID 34944138, 2021). "Moreover, hyperglycemia activated the NLRP3/caspase-1/GSDMD axis to cause pore formation, where GSDMD further aggravated pyroptosis in human retinal pericytes." (PMID 39253076, 2024). "has also suggested that the cleavage of GSDMD by caspase-1 is downstream to hyperglycemia-induced oxidative stress in H9c2 cardiomyoblasts." (PMID 39253076, 2024). "This current study demonstrates that hyperglycemia-induced Müller cell death fulfills all criteria for pyroptosis and links the pro-inflammatory function of caspase-1 and IL-1β production to cell death." (PMID 39483336, 2024). "Knockdown of RIP2 attenuated high glucose-induced caspase-1 activity by 85.8% ± 1.8% demonstrating that RIP2 is necessary for hyperglycemia-induced caspase-1 activity." (PMID 39483336, 2024). "RIP2 is not only involved in hyperglycemia-induced caspase-1 activation but also promotes caspase-1 activation by IL-1β." (PMID 39483336, 2024). "To further establish a hyperglycemia-induced caspase-1/IL-1β/IL-1R1 feedback loop we used isolated human Müller cells (hMC)." (PMID 39483336, 2024). "Previously we have shown that hyperglycemia induces caspase-1 activation and IL-1β production in hMCs." (PMID 39483336, 2024). "Inflammatory factors, such as IL-6, TNF-α, cleaved caspase-1, and pro-IL-1β are downstream of the NF-κB signaling pathway and are also involved in neuroinflammation induced by hyperglycemia." (PMID 38421831, 2024). "Since RIP2 upregulation was crucial for hyperglycemia-driven caspase-1 activation, we further investigated the role of RIP2 in IL-1β-induced caspase-1 activation." (PMID 39483336, 2024). "A similar hyperglycemia-mediated caspase-1/IL-1β/IL-1R1 feedback signaling was detected in vitro in human Müller cells which was prevented by treatment with IL-1ra." (PMID 39483336, 2024). "We were able to show that hyperglycemia initiates caspase-1 activity and IL-1β continues to promote caspase-1 activation." (PMID 39483336, 2024). "For the first time this study shows that RIP2 plays a role in hyperglycemia-mediated caspase-1 activation and cell death in retinal Müller cells." (PMID 39483336, 2024). "Hyperglycemia significantly increased the colocalization of NLRP3 with Caspase-1 in the glomeruli of db/db mice compared to control mice, indicating the formation of NLRP3 inflammasomes in diabetic mice." (PMID 37540330, 2023). "Hyperglycemia can cause NLRP3 to recruit ASC and bind to pro-caspase-1 to form an inflammasome and activate caspase-1." (PMID 36425593, 2022). "A recent study reported that empagliflozin reduced the diabetic pancreatic tissue from hyperglycemia-induced damage of db/db mice via the suppression of the NLRP3/caspase-1/GSDMD pathway." (PMID 35265148, 2022). "UCP2 deficiency further increased the expression of NLRP3 and cleaved caspase 1 in neurons in the context of hyperglycemia-exacerbated cerebral I/R damage." (PMID 33735403, 2021). "Studies have indicated that hyperglycaemia increased the production of ROS to trigger the caspase-1-dependent pyroptosis which mediates important pathological changes in diabetic cardiomyopathy." (PMID 30911553, 2019). "Hyperglycemia can yield inflammation and can induce renal injury by promoting IL-1β and caspase-1 expression in renal cells." (PMID 31119177, 2019). "Our previous study demonstrated that hyperglycemia, a hallmark characteristic of T2DM, induced NLRP3 inflammasome-dependent caspase-1 activation and IL-1β maturation in human monocytic cells." (PMID 28970837, 2017).